APOB (apolipoprotein B)
Diseases named in the same sentence as APOB in open-access papers (continued):
Sharing a sentence is not in itself a finding about the gene and the disease.
Insulin resistance (continued). "For instance, discordant LDL/ApoB may indicate a decreased LDL clearance due to impaired LDL receptors, has been associated with insulin resistance, increased systemic inflammation and lower serum lipids in circulation." (PMID 36247924, 2022). "Thus, chronic excess caloric intake, weight gain, and insulin resistance that occurred during follow-up likely account for some of the apoB increases observed in this analysis." (PMID 36272600, 2022). "The apolipoprotein ratio is associated with insulin resistance in non-diabetic subjects and can therefore be helpful in patients whose phenotypes are independent of apoB." (PMID 34677405, 2021). "Variants of A1CF may, therefore, affect urate metabolism through ApoB production and/or ApoB-related insulin resistance." (PMID 33517564, 2021). "The insulin resistance improved significantly in the intervention group which has shown to reduce the inflammatory markers such as hs-CRP and other cardiovascular risk factors, particularly triglycerides, LDL and ApoB in subjects on LGI diet." (PMID 32867226, 2020). "Because APOB SNPs are related to lipids, the GRS of APOB may be beyond the interval of the association with insulin resistance." (PMID 33005209, 2020). "Overall, these studies indicate that in hepatocytes naringenin reduces ApoB secretion, triglyceride production and gluconeogenesis and these effects may lead to attenuation of hyperglycemia, hyperlipidemia and insulin resistance in vivo." (PMID 30871083, 2019). "However, insulin resistance reduces this sequestering, allowing ApoB to be readily secreted from hepatocytes and drive the formation of VLDLs." (PMID 30871083, 2019). "So it is surmised that ECD can reduce blood glucose through the promotion of insulin secretion and result in the improvement of the apoB saccharification, so as to improve the insulin resistance and reduce the secretion of VLDL and TG in liver, ultimately improving hyperlipidemia." (PMID 26504476, 2015). "It is thought that it may represent a better marker than the apoB/apoA1 ratio for identifying insulin resistance and MS in some populations." (PMID 24688542, 2014). "The results of this randomised clinical trial demonstrated that in forty-two diabetic participants, BVFE produced significant decrease in TG, TC, LDL-c, apoB, insulin resistance, glucose, insulin and significant increase in TAC compared to the placebo group at the end of study." (PMID 24250489, 2012). "In addition to fatty acid-associated lipotoxicity, it has been reported recently that hepatic overexpression of apoB also induce hepatic ER stress and insulin resistance." (PMID 20423497, 2010). "ApoB is a particularly sensitive indicator of changes in glycemic control, so it is possible that tight glycemic control (reduction of insulin resistance in our study) may have ‘antiatherogenic’ effects by lowering ApoB levels (which were also lowered in our study)." (PMID 36788517, 2023). "Data on APOA-I and APOB genetic polymorphisms in insulin resistance and MetS are still lacking." (PMID 33005209, 2020). "However, we found no signifcant difference in HDL-c, homocysteine and HbA1c but LDL-c/HDL-c, TG/HDL-c, apoB/apoA-I and insulin resistance had significant decreases at the end of study in BRFE group compared to the placebo group (p = 0.001, p = 0.003, p = 0.01, and p = 0.01)." (PMID 24250489, 2012). "APOA1, APOB, and APOC4 are core members of the apolipoprotein family that play crucial roles in regulating lipid metabolism and insulin resistance." (PMID 41056021, 2026). "Biochemical variables, triglyceride (TG), high‐density lipoprotein cholesterol (HDL‐C), apolipoprotein A1 (ApoA1), apolipoprotein B (ApoB), fasting serum insulin (FINS), and homeostatic model assessment of insulin resistance (HOMA‐IR) were determined." (PMID 41323197, 2025). "Apo‐A indicates apolipoprotein A‐I; Apo‐B, apolipoprotein B, Apo‐J, apolipoprotein J; and HOMA‐IR, homeostatic model assessment of insulin resistance." (PMID 40123054, 2025).
Insulin resistance (continued). "In our current research, we did observe the occurrence of metabolic dysfunction in the CPZ group, characterized by insulin resistance and alterations in plasma levels of HDL, ApoA1, and ApoB levels." (PMID 38802393, 2024). "Women with PCOS and insulin resistance have significantly increased triglyceride (TG), low-density lipoprotein (LDL), apolipoprotein B (Apo-B), TG/high-density lipoprotein (TG/HDL), and Apo-B/Apo-A levels." (PMID 39734992, 2024). "In a certain part of the population, namely, people with insulin resistance, the measures of LDL cholesterol can be in discordance with apolipoprotein B (apo B) and LDL particle concentration." (PMID 37299535, 2023). "After surgery, the homeostatic model assessment of insulin resistance (HOMA-IR) was significantly reduced (4.4 ± 2.5 vs. 1.2 ± 0.7; P < 0.005), and it was positively related to VLDL1 apoB and TG production." (PMID 37432744, 2023). "TAGs can be used to form VLDL with ApoB, which is secreted from the liver and hepatic secretion of VLDL increases with insulin resistance." (PMID 34327606, 2022). "Hepatic insulin resistance further promotes VLDL production and secretion by increasing apolipoprotein B (apoB) and apoCIII availability/expression." (PMID 35458210, 2022). "Further, the GDM women had a higher estimated insulin resistance, unfavorable lipid ratios (i.e., higher TG/HDL-C, LDL/HDL-C and apoB/apoA), lower estimated insulin sensitivity and lower estimated β-cell function at the 5-year follow-up visit." (PMID 28068986, 2017). "The ApoB/ApoA1 ratio and LDL-C were also reported to be positively correlated with insulin resistance in a Chinese population with abdominal obesity." (PMID 24093822, 2013). "Therefore, insulin resistance may increase the serum level of ApoB." (PMID 24093822, 2013). "Attenuated intracellular degradation of newly synthesized apoB is accompanied with increased VLDL production, as often observed under chronic hyperinsulinemia and insulin resistance conditions." (PMID 20423497, 2010). "In a state of insulin resistance, there is an increased FFAs flux to the liver, which stimulates the synthesis of very low-density lipoprotein (VLDL) particles, which in turn leads to elevated plasma levels of triglycerides (TG) and apolipoprotein B (Apo B)." (PMID 40969373, 2025). "We believe this is related to the presence of insulin resistance in these groups, where circulating insulin inhibits the secretion of VLDL into systemic circulation through complex mechanisms such as the degradation of apolipoprotein B." (PMID 40084133, 2025). "In the ART cohort, the mRNA expression level of SREBP‐1 exhibited a positive correlation with BMI, ApoB, fasting blood glucose, fasting insulin, and the insulin resistance index, whereas it demonstrated a negative correlation with ApoA1." (PMID 41323197, 2025). "Insulin resistance is one of the mechanisms behind high TG levels in obese individuals with cardiometabolic syndrome or T2DM and can increase VLDL production by inhibiting apolipoprotein B degradation, leading also to elevated RC levels." (PMID 39796622, 2025). "Metabolism‐related indicators were mainly monitored in this study including triglyceride (TG), HDL‐C, serum apolipoprotein A1 (ApoA1), serum apolipoprotein B (ApoB), fasting serum insulin (FINS), and homeostatic model assessment of insulin resistance (HOMA‐IR)." (PMID 41323197, 2025). "Nevertheless, excess VAT, regardless of BMI, has been related to insulin resistance and atherogenic factors such as hypertriglyceridemia and increased apolipoprotein B levels." (PMID 39599733, 2024). "At the baseline and at the end of the study, blood glucose levels, homeostatic model assessment of insulin resistance (HOMA-IR) and the homeostatic model assessment of β-cell dysfunction (HOMA-B), as well as apolipoprotein A-I (ApoA1) and apolipoprotein B (ApoB) were measured." (PMID 36788517, 2023).
Insulin resistance (continued). "Apolipoprotein B-100 (ApoB), an essential component of VLDLs and its metabolites and a key structural protein component of all major atherogenic lipoproteins, is a good indicator of CVD, insulin resistance, MetS and inflammation." (PMID 36829843, 2023). "Additionally, hepatic insulin resistance reduces VLDL synthesis and apoB lipoprotein catabolism, resulting in an atherogenic lipid pattern characterized by increased triglyceride concentrations, as observed in NGT-1h-high individuals." (PMID 36613109, 2022). "Insulin resistance, which is a prominent feature of T2DM, may be one of the factors responsible for elevated apolipoprotein B-100 levels in our study subjects." (PMID 32867226, 2020). "Moreover, the discordance (LDL-particle number > apoB) increases with greater insulin resistance, suggesting that apoB underestimates LDL particle number in patients with insulin resistance that is typically accompanied by hypertriglyceridemia." (PMID 28125987, 2017). "Circulating endothelin-1 levels were associated with both insulin resistance (HOMA-IR) and apoB/apoA1 ratio in men whereas no such associations were observed in women." (PMID 26573599, 2015). "Research now demonstrates that apolipoprotein B and non‐HDL cholesterol more accurately reflect atherogenic lipoprotein burden than LDL cholesterol alone, while the triglyceride‐to‐HDL cholesterol ratio is a useful marker of insulin resistance and metabolic dysfunction." (PMID 41994668, 2026). "Notably, the boost value does not perfectly segregate insulin resistance from lipid loci; for example, APOB, a known lipoprotein structural component, had a strongly positive boost score (TG/HDLBS = 5.5)." (PMID 39277575, 2024). "Studies have proven the NonHDLc/HDLc ratio to be a better predictor for CVD than NonHDLc, as well as a better predictor for insulin resistance and MS than the apoB/apoA1 ratio (difference might be attributed to dysfunctional HDL levels)." (PMID 30131058, 2018). "These metabolic events are in part attributed to insulin resistance and account for our finding that MHO participants have less insulin resistance and higher apoA-I, possibly accounting for a less atherogenic effect, particularly when combined with lower apoB and the apoB : apoA-I ratio." (PMID 28473926, 2017). "Third, enhanced hepatic synthesis of apoB and VLDL-C might be triggered by insulin resistance." (PMID 28596946, 2017). "Insulin resistance elevates the VLDL and apolipoprotein (apo) B-containing lipoproteins concurrently diminishing the suppressive effect of insulin on apo B secretion either by reducing apoB degradation or by inhibition of microsomal TG transfer protein activity." (PMID 26582144, 2015). "The favorable effects of AI, comprising the improvement of HFD-induced insulin resistance and the downregulation of molecules involved in VLDL assembly in the liver, might be partially reflected in decreased plasma concentrations of triglyceride and ApoB protein." (PMID 28805698, 2017). "Reduced PI3K activity in animal models, secondary to insulin resistance, has been reported to increase the expression of protein-tyrosine phosphatase 1B (PTP-1B), leading to suppression of ER60, a protease associated with the ER, which promotes ApoB degradation via a non-proteasomal pathway." (PMID 25725623, 2015). "Insulin resistance in our study was not related to either apolipoprotein A1 (ApoA1), the major apolipoprotein in HDL particles, or apolipoprotein B (ApoB), the major apolipoprotein in TG-rich lipoprotein VLDL and LDL." (PMID 36979405, 2023). "Significant differences were observed in fasting insulin, homeostasis model assessment of insulin resistance (HOMA-IR), TG, TC, LDL-C, non-HDL-C, TRLRs, ApoB, ApoCIII, ApoAI/ApoB and ApoCII/ApoCIII values between the two groups." (PMID 33967959, 2021).
Insulin resistance (continued). "A recent study found that non-HDL-c/HDL-c was a better indicator than apolipoprotein B (ApoB)/apolipoprotein A1 (ApoA1) and ApoB/LDL-c in identifying MetS and insulin resistance." (PMID 24555711, 2014). "Furthermore, postsurgery VLDL1 apoB and TG production rates, but not those of VLDL2, were positively correlated with insulin resistance." (PMID 37432744, 2023). "In non-diabetic patients, apoB—but not LDL-C—corresponded positively with dysfunctional white adipose tissue and delayed clearance of fat, hyperinsulinemia, insulin resistance, and activation of the IL-1β system, all of which are known risk factors for type 2 diabetes." (PMID 34677405, 2021).
type 2 diabetes (173 papers, 2004 to 2026). "In terms of CVD risk factors, BMI, dyslipidaemia and Type II diabetes mellitus (T2DM) were reported to positively associate with ApoB and ApoB: ApoA1 and negatively with ApoA1 among adolescents from Brazil and adults from China." (PMID 40375303, 2025). "The association between ApoB and CA risk involved four mediators: Type 2 diabetes (82.7%), WC (19.9%), AP (25.2%), and DBP (57.9%)." (PMID 40575595, 2025). "The V162 minor allele is associated with an increase in triglycerides, total cholesterol, LDL, ApoB, ApoC3, the risk of type 2 diabetes, and a decrease in HDL." (PMID 40806580, 2025). "The inverse association of liability to type 2 diabetes with apoB became pronounced in men after excluding SNPs explaining more of the variance in the outcome than in the exposure (p values for sex difference 0.001)." (PMID 36624450, 2023). "Genetically predicted apoB and Lp(a) had little association with type 2 diabetes or glycemic traits in women or men." (PMID 36624450, 2023). "In the multivariable MR analyses, the associations of apoB with type 2 diabetes and glycemic traits were similar when taking into account TG and Lp(a)." (PMID 36624450, 2023). "Genetic liability to type 2 diabetes was associated with higher TG in women, and possibly with lower apoB in men (p values for sex difference 0.002 and 0.067, respectively)." (PMID 36624450, 2023). "Genetic liability to type 2 diabetes was associated with higher TG in women, and possibly with lower apoB in men." (PMID 36624450, 2023). "Other studies have shown that DPP4 genetic polymorphisms in type 2 diabetes are associated with serum lipid levels, with an allele mutation of A to G in rs3788979 being associated with reduced ApoB level." (PMID 35190847, 2022). "After restricting to traits thought to be causes of liability to type 2 diabetes, six traits remained: apolipoprotein B, diastolic BP, fasting insulin, hip circumference, total cholesterol and trunk fat percentage (where variable ‘stage2_pad’ is true)." (PMID 35129650, 2022). "We also similarly assessed associations with traditional IHD risk factors, i.e., blood pressure, type 2 diabetes, glycated hemoglobin (HbA1c), and with plasma apoB given it is increasingly being considered as an important cause of IHD37–39." (PMID 33927215, 2021). "By contrast, a higher apoB was associated with a lower risk of type 2 diabetes in univariable mendelian randomisation, but in multivariable mendelian randomisation, a strong, positive association between apoB and risk of type 2 diabetes emerged." (PMID 34729547, 2021). "The apoB/apoA-1 ratio already about 20 years in advance is associated with development of type 2 diabetes, as seen in the AMORIS cohort." (PMID 34851955, 2021). "The association of ApoB with incident type 2 diabetes has been proven with improved risk prediction compared to LDL-C or HDL-C." (PMID 24093822, 2013). "VLDL overproduction and the loss of insulin suppression of apoB secretion occur in patients with type 2 diabetes." (PMID 23617853, 2013). "We also assessed sex-specific associations of liability to type 2 diabetes with apoB, TG and Lp(a)." (PMID 36624450, 2023). "We also applied univariable mendelian randomisation to evaluate evidence of a bidirectional association between apoB and type 2 diabetes (ie, whether genetic liability to type 2 diabetes affects apoB levels)." (PMID 34729547, 2021). "ApoB is highly associated with type 2 diabetes and research has shown that apoB levels may be a risk factor for type 2 diabetes." (PMID 34677405, 2021). "In multivariable mendelian randomisation, the direction of effect was reversed: higher apoB was associated with elevated risk of type 2 diabetes (mothers: 1·34, 1·06–1·70, FDR-adjusted p=0·041), although the increase in risk was weaker in fathers (1·17; 0·94–1·46, FDR-adjusted p=0·24)." (PMID 34729547, 2021).